REN (renin)
Diseases named in the same sentence as REN in open-access papers (continued):
Sharing a sentence is not in itself a finding about the gene and the disease.
chronic kidney disease (continued). "Furthermore, it has been reported that stopping inhibitors of the renin-angiotensin system in patients with advanced chronic kidney disease delayed the onset of renal replacement therapy in the majority of the patients." (PMID 26371050, 2015). "In patients with chronic renal disease, a slow, gradual decrease in the level of 1,25-dihydroxyvitamin D (calcitriol) and erythropoietin is observed whilst different mechanisms bring to increased activation of the renin-angiotensin system." (PMID 26000281, 2015). "Patients with chronic kidney disease (CKD) frequently experience cardiovascular events, and as per current therapeutic guidelines, renin-angiotensin system inhibitors (RASi) can protect the cardiovascular system in those with proteinuric CKD." (PMID 41530463, 2026). "Since there are effective measures to slow the progression of chronic kidney disease (CKD), such as blockage of the renin–angiotensin–aldosterone system and strict blood pressure control, early identification of CKD is paramount." (PMID 40003341, 2025). "Pharmacologic inhibition or blockade of the renin-angiotensin system (RAS) is part of the standard management to slow the progression of many forms of chronic kidney disease (CKD)." (PMID 39766282, 2024). "In the study of chronic kidney disease (CKD), melatonin can be used for targeting the intrarenal renin-angiotensin system, delaying kidney injury, and improving sleep disorders and blood pressure rhythm changes in CKD." (PMID 35979396, 2022). "Multi-factors, such as anorexia, activation of renin-angiotensin system, inflammation, and metabolic acidosis, contribute to malnutrition in chronic kidney disease (CKD) patients." (PMID 33917381, 2021). "Inhibition of the renin-angiotensin system (RAS) is a cornerstone of managing chronic kidney disease (CKD) patients with proteinuria including diabetic nephropathy and glomerulonephritis." (PMID 32410703, 2020). "Chronic kidney disease (CKD) exhibits progressive kidney dysfunction and leads to disturbed homeostasis, including accumulation of uremic toxins, activated renin-angiotensin system, and increased oxidative stress and proinflammatory cytokines." (PMID 33419312, 2020). "Chronic kidney disease (CKD) is one of the most common progressive diseases in older cats and the renin–angiotensin–aldosterone system (RAAS) is known to play a key role in the progression of the disease." (PMID 30345862, 2019). "For example, after withdrawal of allopurinol in patients with chronic kidney disease and mild hyperuricemia, increase in blood pressure and worsening of serum creatinine were only observed in patients without being under medication by pharmacological blockers of the renin-angiotensin system." (PMID 30940115, 2019). "Oxidative stress induced by hyperuricemia is closely associated with the renin-angiotensin system, as well as the onset and progression of cardiovascular disease (CVD) and chronic kidney disease (CKD)." (PMID 29967665, 2018). "Activation of the renin-angiotensin system may initiate chronic kidney disease." (PMID 30397212, 2018). "The present study is aimed at unraveling the potential modifier effect of the REN gene tag-SNP on the progression of chronic kidney disease (CKD) in ADPKD." (PMID 26753721, 2016). "Blood pressure (BP) control and reduction of urinary protein excretion using agents that block the renin–angiotensin aldosterone system are the mainstay of therapy for chronic kidney disease (CKD)." (PMID 26429974, 2016). "Activation of the renin-angiotensin-aldosterone system (RAAS) is a major hallmark in the development and progression of organ damage in chronic kidney disease (CKD)." (PMID 27732567, 2016). "The activation of the renin-angiotensin-aldosterone (Aldo) system (RAAS) is a major hallmark in the development and progression of organ damage in chronic kidney diseases (CKD)." (PMID 27244896, 2016).
chronic kidney disease (continued). "inhibition of the renin-angiotensin-aldosterone system (RAAS) plays a pivotal role in treatment of chronic kidney diseases (CKD)." (PMID 27009050, 2016). "The search for new therapies providing cardiorenal protection in chronic kidney disease (CKD) has led to treatments that combine conventional renin-angiotensin-aldosterone-system inhibitors with other drugs that exhibit potential in disease management." (PMID 25300759, 2014). "Renin-angiotensin-aldosterone inhibitors were used in two-thirds of the patients either as single agent or in combination (n = 34,75.6%), whilst the remaining 11 patients were on neither for reasons such as hyperkalaemia or development of acute on chronic renal failure." (PMID 24883149, 2014). "Salt sensitivity has been found to have a higher prevalence in certain populations: older age, blacks, insulin resistance, microalbuminuria, chronic kidney disease (CKD), and low renin level." (PMID 23691281, 2013). "Dyslipidemia and activation of renin-angiotensin system (RAS) contribute to the progression of chronic kidney disease (CKD)." (PMID 23570453, 2013). "Although renin may have profibrotic effects mediated by (pro)renin receptor activation, this report raises questions on the potential consequences of local renin activation on chronic kidney disease in patients with dual angiotensin blockade." (PMID 22533828, 2012). "The renin-angiotensin-aldosterone system (RAAS) plays an important role in the progression of chronic kidney disease (CKD)." (PMID 22917002, 2012). "Drugs targeting the renin-angiotensin-aldosterone system (RAAS) are the mainstay of therapy to retard the progression of proteinuric chronic kidney disease (CKD) such as diabetic nephropathy." (PMID 22701794, 2012). "Experimental evidence suggests that in individuals with chronic kidney disease (CKD), elevated FGF-23 levels diminish calcitriol synthesis and contribute to the activation of the RAAS, potentially leading to increased renin production." (PMID 39989455, 2025). "CKD denotes chronic kidney disease; T2D, type 2 diabetes; SD, standard deviation; SGLT2, sodium glucose transport-2; RAS, renin-angiotensin system; MRA, mineral corticoid antagonists; DPP-4, Dipeptidyl peptidase-4; GLP-1, glucagon-like peptide-1." (PMID 40676552, 2025). "The incidence of HK is even high in patients with comorbidities such as chronic kidney disease (CKD), heart failure (HF), type 2 diabetes, and hypertension, and those treated with renin–angiotensin–aldosterone system inhibitors (RAASis)." (PMID 39135788, 2024). "Renin-angiotensin-aldosterone system inhibition (RAASi) reduces intraglomerular pressure and is a standard therapy for dogs with proteinuric chronic kidney disease (CKD)." (PMID 39711803, 2024). "Various mechanisms are involved in the pathogenesis of chronic kidney disease (CKD) including an inflammatory response, the activation of the renin–angiotensin–aldosterone system, and hyperfiltration." (PMID 36836636, 2023). "In particular, changes in electrolytes, pH, the activation of the autonomic nervous system (ANS), the renin–angiotensin–aldosterone system (RAAS), and proarrhythmogenicity of uremic toxins contribute to arrhythmogenesis in chronic kidney disease." (PMID 37762501, 2023). "The kidney is one of the most commonly affected organs in HUA, which promotes the development of chronic kidney disease (CKD) by damaging endothelial cells, activating the renin-angiotensin system (RAS), and promoting inflammatory responses." (PMID 35909538, 2022). "Regardless of the cause and severity, chronic kidney disease alone is sufficient to stimulate the adrenergic system to increase renal renalase synthesis due to a low level of inflammation, activation of oxidative stress and the renin-angiotensin-aldosterone system." (PMID 34200667, 2021).
chronic kidney disease (continued). "Obstructive sleep apnea (OSA) is common in patients with chronic kidney disease (CKD) and may contribute to kidney injury by activation of the renin–angiotensin system (RAS)." (PMID 32207249, 2020). "Cardiovascular (CV) abnormalities such as left ventricular hypertrophy (LVH) and left ventricular (LV) dysfunction are common in patients with chronic kidney disease (CKD) due to chronic inflammation, activation of the renin-angiotensin-aldosterone system and changes in hemodynamics." (PMID 32722021, 2020). "Blockade of the renin-angiotensin system (RAS) with angiotensin-converting enzyme inhibitors (ACEi) or angiotensin-receptor blockers (ARBs) is a critical component of chronic kidney disease (CKD) management." (PMID 31278281, 2019). "The utilization of renin-angiotensin-aldosterone system blockers and improvements in glycemic, blood pressure, and lipid control slow the progression of chronic kidney disease (CKD) to a degree." (PMID 31636737, 2019). "Urinary angiotensinogen (UAGT) level has been shown highly correlated with intrarenal renin-angiotensin system (RAS) activity and severity of chronic kidney diseases (CKD)." (PMID 30541470, 2018). "In patients with chronic kidney disease (CKD) and patients on dialysis, an increased activation of the sympathetic nervous system, increased renin secretion, and increased activity of the renin-angiotensin-aldosterone system after bilateral nephrectomy were observed." (PMID 28728576, 2017). "Consequently the beneficial effects of vitamin D receptor activators in experimental chronic renal failure could be related to downregulation of the renal renin-angiotensin system and in particular to a reduced renin build-up caused by the disruption of the feedback inhibition loop." (PMID 26000281, 2015). "Renin-angiotensin system (RAS) plays a pivotal role in chronic kidney disease (CKD)." (PMID 24614509, 2014). "Other medications such as renin–angiotensin–aldosterone system (RAAS) blockers can lead to acute kidney injury (AKI), hyperkalaemia or hypotension, with further deterioration in renal function, especially in those with chronic kidney disease (CKD)." (PMID 40863223, 2025). "CKD: Chronic kidney disease; RAAS: Renin-angiotensin-aldosterone system; BMI: Body mass index; SBP: systolic blood pressure; DBP: diastolic blood pressure; PWV: Pulse wave velocity; ACR: Albumin creatinine ratio; e-GFR: Estimated glomerular filtration rate; U/S: Ultrasound examination." (PMID 37198541, 2023). "The vicious circles between type 2 diabetes (T2D), chronic kidney disease (CKD) and heart failure (HF) are underpinned by several common pathophysiological mechanisms, including sodium retention and the upregulation of the renin-angiotensin-aldosterone system (RAAS)." (PMID 36015195, 2022). "Therefore, we hypothesized that sodium bicarbonate supplementation reduces urinary renin excretion in patients with chronic kidney disease (CKD) and metabolic acidosis." (PMID 33382448, 2021). "For patients with CKD, the role of the renin-angiotensin system modulation only exerts partial salutary effects and can not necessarily prevent the progression to end-stage renal disease and the need for renal replacement therapy." (PMID 30572886, 2018). "We hypothesize that in our experimental model of chronic kidney disease (CKD) due to ischemia with increased activity of the renin–angiotensin–aldosterone system (RAAS), renal denervation can have protective effects by slowing or blocking the progression of renal injury." (PMID 29070043, 2017). "In this exploratory short-term study, we demonstrated that treatment with a renin inhibitor, aliskiren, significantly reduced proteinuria in patients with nondiabetic chronic kidney diseases." (PMID 23326865, 2012). "The renin-angiotensin system had been postulated as a player in the pathogenesis of NAFLD and chronic kidney disease (CKD)." (PMID 38691315, 2024).
chronic kidney disease (continued). "The renin-angiotensin-aldosterone system (RAAS) is influential in chronic kidney disease (CKD) pathophysiology, and RAAS activation is a crucial factor in CKD progression in humans." (PMID 38756510, 2024). "Among the drugs that have been shown to slow the progression of chronic kidney disease are glucagon-like peptide 1 receptor agonists, sodium-glucose cotransporter-2 inhibitors, renin-angiotensin system inhibitors, and, more recently, non-steroidal mineralocorticoid receptor antagonists." (PMID 38012781, 2023). "AKI may lead to activation of the renin-angiotensin system (RAS), persistent chronic inflammatory damage, progressive renal fibrosis, and eventual progression to chronic kidney disease (CKD) or end stage renal disease (ESRD)." (PMID 38034989, 2023). "In the past decades, the only treatment strategy considered effective for diabetic nephropathy was blockade of the renin–angiotensin system (RAS), but many patients still develop to chronic kidney disease (CKD) or end-stage renal disease (ESRD)." (PMID 35057768, 2022). "Abnormal renin-angiotensin system (RAS) activation plays a critical role in the initiation and progression of chronic kidney disease (CKD) by directly mediating renal tubular cell apoptosis." (PMID 31857626, 2019). "Activation of the renin-angiotensin system (RAS) promotes the occurrence and development of chronic kidney diseases (CKD)." (PMID 31623681, 2019). "The activation of the renin-angiotensin system (RAS) is closely related to the progression and development of cardiovascular disease (CVD) and chronic kidney disease (CKD)." (PMID 29967665, 2018). "Therefore, pharmacological inhibition of the renin–angiotensin–aldosterone system (RAAS) may have a beneficial impact on the progression of proteinuria and chronic kidney disease." (PMID 23326865, 2012). "In addition, reduced renin secretion is often observed in patients with sclerosis of the juxtaglomerular apparatus or renal vascular changes, but none of our patients had severe or end-stage renal disease." (PMID 39416427, 2024). "Patients without chronic kidney disease (CKD) (group eGFR ≥60/Alb−) most commonly used renin-angiotensin-aldosterone-system inhibition (RAASi) (59%), followed by β-blockers (39%), and thiazide diuretics (32%)." (PMID 28684676, 2017). "Classical renin–angiotensin system inhibitors (RASI), such as angiotensin-converting enzyme inhibitors (ACEi) and angiotensin receptor blockers (ARB), have long been the foundation of treatment for patients with cardiovascular disease (CVD) and chronic kidney disease (CKD)." (PMID 40755965, 2025). "Renin-angiotensin-aldosterone (RAAS) blockade is acclaimed, by consensus, to be renoprotective in both diabetic and non-diabetic chronic kidney disease (CKD)." (PMID 36447726, 2022). "However, several PA cases with unsuppressed plasma renin activity (PRA) and “normal” range ARR values have been reported, and these cases have a relatively long history of PA and chronic kidney disease (CKD)." (PMID 32089681, 2020). "Accumulation of cardiovascular risk factors, including dyslipidemia, hypertension, and diabetes, activates the renin-angiotensin-aldosterone system (RAAS), leading to not only ischemic cardiovascular disease (CVD) but also left ventricular (LV) dysfunction and chronic kidney disease (CKD)." (PMID 22792467, 2012). "Unquestionably, there is a common consensus regarding cardiorenal protection with renin-angiotensin-aldosterone system blockade (RAASB) in both diabetic and nondiabetic chronic kidney disease (CKD)." (PMID 38161827, 2023).
Hypokalemia (241 papers, 2005 to 2026). An abnormally decreased potassium concentration in the blood. "Typically, elevated plasma renin activity, secondary hyperaldosteronism, and hypokalemia are considered key diagnostic features and often guide clinicians toward the suspicion of a renin-secreting tumor." (PMID 41357681, 2026). "In clinical practice, hypokalemia is usually closely associated with elevated levels of renin or aldosterone." (PMID 40873624, 2025). "The cause of severe, persistent hypokalemia and metabolic alkalosis with low renin and (presumed) aldosterone levels in our patient was due to excessive licorice consumption." (PMID 40672027, 2025). "This leads to increased sodium reabsorption, which can cause hypokalemia, metabolic alkalosis, low renin and aldosterone levels, and early onset salt-sensitive hypertension in patients with Liddle syndrome." (PMID 38691164, 2024). "BS is a group of autosomal recessive renal tubular diseases manifested by hypokalemia, renal salt loss, metabolic alkalosis, elevated renin and aldosterone levels, and normal blood pressure." (PMID 37131142, 2023). "More specifically, on day 5, renin was undetectable, aldosterone was increased and associated with hypokalemia." (PMID 36926028, 2023). "A possible reason for hypokalemia in EH is that some forms of EH are also associated with low renin levels, and hypokalemia can be an important finding in this form of EH." (PMID 34220715, 2021). "The main reason for the incidence of hyponatremia was presumed to be amplified antidiuretics hormone secretion (ADH) while hypokalemia was attributed to renin-angiotensin-aldosterone activation resulting in the loss of potassium in the urine." (PMID 33062534, 2020). "It is currently assumed that, in dietary chloride deficiency, hypokalemia results from a potassium redistribution from the extracellular to the intracellular compartment, and from an activation of the renin–angiotensin–aldosterone system." (PMID 33182508, 2020). "The final consequences comprise elevated BP, sodium and water retention, decreased plasma potassium (hypokalemia) and caused a suppression of plasma renin and aldosterone levels." (PMID 31615045, 2019). "Hypokalemia, the leading symptom, was observed in all patients and was associated with metabolic alkalosis and overactivity of the renin-angiotensin-aldosterone system (RAAS)." (PMID 28288174, 2017). "Laboratory investigationsconfirmed the hypokalaemia and his serum potassium level wasnow 2.7 mmol/l, associated with a supressed renin level of 6.0 mIU/l and aldosterone of 48.6 pmol/l." (PMID 29144530, 2017). "It is caused by gain-of-function mutations of the kidney epithelial sodium channel (ENaC) and it is classically associated with hypokalemia and suppression of renin and aldosterone." (PMID 25210634, 2014). "The reduction in urinary concentrating ability caused by hypokalemia is primarily attributed to the downregulation of aquaporin channels; however, the hyperactivation of the renin–angiotensin system, leading to increased sodium reabsorption in the proximal tubules, is also suspected to be involved." (PMID 40711676, 2025). "Vitamin D3 deficiency, commonly observed in PHP1B, may exacerbate hypokalemia through activation of the renin–angiotensin system." (PMID 40893942, 2025). "The key finding in this study showed that a plasma aldosterone concentration of > 20 ng/dL, plasma renin activity of < 0.6 ng/ml/hr and presence of spontaneous hypokalemia had an overall satisfactory diagnostic performance as compared with other combination parameters." (PMID 38978003, 2024). "Whereas in Na+ transport defects in the distal nephron, hypokalemia usually indicates compensatory activation of the renin–angiotensin–aldosterone system and is associated with alkalosis, the homozygous Kir5.1 defect also leads to hypokalemia, but mostly in association with acidosis." (PMID 35370765, 2022).